INS (insulin)
Diseases named in the same sentence as INS in open-access papers (continued):
Sharing a sentence is not in itself a finding about the gene and the disease.
type 1 diabetes (continued). "T1D, as an autoimmune disease in which the patient's own immune system destroys insulin-secreting β-cells in the pancreas, and genetic factors play an important role in the onset, progression, and eventual clinical diagnosis of type 1 diabetes." (PMID 37957681, 2023). "In this review we describe the metabolic changes that occur in the early pre-symptomatic stages of type 1 diabetes with respect to both insulin secretion and insulin sensitivity, as well as the measurable outcomes that can be derived from the available tests." (PMID 37712956, 2023). "In Type-1 diabetes, the human pancreas loses its ability to produce insulin to regulate elevated sugar levels." (PMID 36766445, 2023). "Both approaches are promising; however, at present, there is no doubt that it is artificial intelligence that can stand up as the most promising technology to achieve the most physiological replacement of insulin delivery in type 1 diabetes." (PMID 37685946, 2023). "In type 1 diabetics, insufficient insulin secretion reduces the ability to store glucose in muscle and adipose tissue, or otherwise in the liver, thus exacerbating chronic hyperglycemia." (PMID 36836895, 2023). "Type 1 diabetes (T1D) is an autoimmune disease that results from the immune-mediated destruction of insulin-producing β cells within pancreatic islets that develops in distinct stages before the onset of clinical symptoms." (PMID 38064552, 2023). "Type 1 diabetes (T1D) is featured by the failure of insulin production due to the destruction of pancreatic β-cells caused by autoimmunity mediated by T-cells." (PMID 37780623, 2023). "In the streptozotocin-induced model of type 1 diabetes, fisetin improved blood glucose, plasma insulin, and glycosylated hemoglobin levels." (PMID 37047807, 2023). "Exogenous insulin, used for the treatment of type 1 diabetes since 1922, remains the current standard of care." (PMID 37221247, 2023). "Type 1 diabetes (T1D) is a chronic autoimmune disease that originates from the destruction of pancreatic β-cells, which are responsible for insulin production and therefore control glucose metabolism." (PMID 37762419, 2023). "Type 1 diabetes is an autoimmune disease that arises due to the destruction of the insulin-producing beta cells in the islets of the pancreas." (PMID 37745723, 2023). "Compared to only GADA-positive adult diabetic patients, those with multiple antibodies exhibited characteristics more similar to those of type 1 diabetes, with a younger age at disease onset, lower BMI, lower C-peptide level, and higher insulin sensitivity." (PMID 37761002, 2023). "In the study group of adult patients with type 1 diabetes treated with continuous infusion of insulin with insulin pump, the microbiota in particular niches of the oral cavity was significantly different." (PMID 36767617, 2023). "In contrast, age did not affect the rate of change of declining beta cell glucose sensitivity or insulin sensitivity in individuals who progressed to a clinical diagnosis of type 1 diabetes." (PMID 36459177, 2023). "The aim of this systematic review is to reveal more solid information about the impact of the menstrual cycle on glycaemic outcomes and insulin sensitivity in type 1 diabetes and highlight the less researched areas." (PMID 36836608, 2023). "The evidence is that Type 1 diabetes reduces the secretion of insulin hormones and hinders the ability of patients to maintain proper glucose levels in the body, leading to multiple health issues." (PMID 36776951, 2023). "Type 1 diabetes (T1D) is an endocrine disorder in which pancreatic β cells stop producing insulin, typically due to autoimmune destruction." (PMID 37377963, 2023). "In type I diabetes, the body’s immune cells destroy insulin-producing pancreatic beta cells, preventing glucose from entering fat or muscle cells, which in turn boosts the production of adenosine triphosphate." (PMID 36986680, 2023).
type 1 diabetes (continued). "Continuous glucose monitors, wearable insulin pumps, and mobile applications have improved patient compliance and outcomes in managing Type 1 diabetes with exogenous insulin." (PMID 37359825, 2023). "Type 1 diabetes (T1D) is associated with the decreased production of insulin through the destruction of pancreatic beta cells, requiring expensive, lifelong recombinant insulin injections." (PMID 36830626, 2023). "Since the β-cells’ major product is insulin, type I diabetes is the disorder given by NC := ’β-cell ‘, NH := ’insulin ‘, DirHF := ’hypo’ and FCB := ‘secretion’ diagnosed as OCH = ‘β-cell insulin hyposecretion’ using OCF := NCNHDirHFFCB." (PMID 37525189, 2023). "From study entry to stage 3 type 1 diabetes onset, beta cell glucose sensitivity and insulin sensitivity declined in both progressor groups." (PMID 36459177, 2023). "Pancreas transplantation is the only treatment option for type 1 diabetes (T1D) patients that provides optimal glycemic control and restores insulin independence." (PMID 37174997, 2023). "With the introduction of insulin therapy, the knowledge of low-carb diets in type 1 diabetes became mostly forgotten." (PMID 37584373, 2023). "Insulin therapy, pancreas transplantation and β cell regeneration are among the suggested treatment strategies for type 1 diabetes." (PMID 36647783, 2023). "Islet autoantibodies, including those directed at insulin, predict type 1 diabetes (T1D) in mice and humans and signal immune tolerance breach by B lymphocytes." (PMID 37261716, 2023). "Type I diabetes mellitus is a chronic life-threatening disease due to the degradation of the β-cells of the pancreas, the cells that make insulin." (PMID 37240841, 2023). "We demonstrate this approach in type 1 diabetes (T1D) trials aiming to preserve endogenous insulin secretion measured by C-peptide." (PMID 37940642, 2023). "Recent data from the Type 1 diabetes exchange suggest an insulin pump rate of 63% among youth in the United States (US), indicating the pump rate in our sample is representative of youth in the US." (PMID 40303274, 2023). "It has been shown that the ketogenic diet can reduce the requirement for insulin in type 1 diabetes patients using insulin pumps by as much as 44.3%." (PMID 36771207, 2023). "INS transcript UTR variants rs689 and rs3842753, associated with type 1 diabetes, are found in many pancreatic RNAseq datasets with an elevation of the 3′UTR alternatively spliced INS transcript." (PMID 36830626, 2023). "In individuals with type 1 diabetes, the presence of eating disorders often involves dangerous behaviors such as insulin restriction to control weight." (PMID 37764739, 2023). "Long-duration studies suggest much higher levels of retained endogenous insulin secretion than in other type 1 diabetes populations." (PMID 36778553, 2023). "The standard insulin therapy regimen in people with type 1 diabetes is either basal-bolus therapy or the use of insulin pumps." (PMID 38089060, 2023). "Among the retrospective studies published, three of them assessed patients exclusively with type 1 diabetes (T1D) and included patients who used insulin pumps or MDI as methods of treatment and either CGM or FGM as glycemic monitoring methods." (PMID 37685740, 2023). "Low C-peptide (approximately <200–300 pmol/l) confirms the treatment requirements of type 1 diabetes, including insulin requirement." (PMID 37728732, 2023). "A "honeymoon" phase is a transient period of type 1 diabetes (T1D) remission, characterized by a significant reduction in insulin requirements and good glycemic control due to a temporary restoration of pancreatic β-cell function." (PMID 36874737, 2023). "Participants (58% women) had a mean age of 47 (SD 15) years, duration of type 1 diabetes of 27 (SD 13) years, BMI of 28.3 (SD 4.2) kg/m2, total daily insulin dose of 45 (SD 20) U and HbA1c level of 56 (SD 6) mmol/mol (7.3% [SD 0.5])." (PMID 37037948, 2023).
type 1 diabetes (continued). "While insulin has been widely studied for its role in glucose homeostasis and islet autoimmunity in type 1 diabetes, little is known about alternative INS-derived proteins." (PMID 36884057, 2023). "Immunofluorescence staining with insulin antibody showed that injection of streptozotocin destroyed the islets accompanied with high blood glucose levels, indicating that the model of type 1 diabetic mice was generated." (PMID 37289842, 2023). "In youth with type 1 diabetes, there is a strong relationship between food intake, insulin therapy, and metabolic control that requires self-regulation." (PMID 37049563, 2023). "Fewer participants with prior early-stage diagnosis had ketonuria (22.2% vs 78.4%, p<0.001) or required insulin treatment (72.3% vs 98.1%, p<0.05) and only 2.5% presented with diabetic ketoacidosis at diagnosis of stage 3 type 1 diabetes." (PMID 37329450, 2023). "Diabulimia is a disordered eating behavior in people with type 1 diabetes who intentionally withhold insulin injections to lose weight." (PMID 38041170, 2023). "Type-1 diabetes is an autoimmune disease characterized by autoimmune damage to pancreatic insulin-producing beta cells." (PMID 36901457, 2023). "The current study is unique in that it combined multiple aspects of life with insulin pump-treated type 1 diabetes—self-reported and register-derived—in the same model whereby we were able to evaluate multicollinearity and estimate relative effect sizes." (PMID 37160785, 2023). "Insulin-dependent diabetes (IDD) refers to a wide range of diabetic conditions characterized by absolute insufficiency of insulin secretion." (PMID 36978130, 2023). "Destruction of β cells by auto-reactive CD8+ T cells in the pancreas leads to the development of type 1 diabetes (T1D), a devastating chronic autoimmune disease that ultimately results in chronic hyperglycemia and a need for lifelong insulin therapy." (PMID 37886648, 2023). "Type 1 diabetes (T1D) is an autoimmune disease in which the immune system attacks insulin‐producing beta cells in the pancreas." (PMID 37476069, 2023). "Those diagnosed with type 1 diabetes need daily injections of insulin to survive and keep their blood glucose within acceptable levels." (PMID 37033222, 2023). "These beneficial effects were also present when a GCGR antagonist was combined with basal and prandial insulin treatment in type 1 diabetes patients." (PMID 36404376, 2023). "One feature appearing to markedly vary with age of type 1 diabetes onset is clinician practice: despite similar clinical presentation, adults with type 1 diabetes appear to be less frequently identified or initially treated with insulin." (PMID 37728732, 2023). "Inclusion criteria were age ≥ 18 years, diagnosis of type 1 diabetes from ≥ 1 year, stable insulin treatment in the last three months, use of real-time CGM, and CGM wear time ≥ 70%." (PMID 37096234, 2023). "We interviewed (n = 19) healthcare professionals who supported pregnant women using CamAPS FX closed-loop during the Automated insulin Delivery Amongst Pregnant women with Type 1 diabetes (AiDAPT) trial." (PMID 36662589, 2023). "A 2016 study also indicated the increased probability of death among patients with type 1 diabetes due to the critical shortage of insulin supply." (PMID 37651138, 2023). "Type 1 diabetes (T1D) is an autoimmune disease resulting in the destruction of insulin-producing β-cells in the pancreas." (PMID 37509587, 2023). "Closed-loop systems for automated insulin delivery are now the standard of care in type 1 diabetes (T1D) management, helping people living with diabetes better manage their glucose while reducing burden." (PMID 36914699, 2023). "Anti-CD3 treatment also demonstrated efficacy in multiple randomized trials in patients with recent-onset type 1 diabetes, transiently preserving β cells’ insulin secretory capacity." (PMID 37458220, 2023).
type 1 diabetes (continued). "In type 1 diabetes, apelin therapy (400 pmol/kg) for 10 weeks enhanced pancreatic islet mass, insulin content, and reduced endoplasmic reticulum stress in the pancreatic islets." (PMID 37424869, 2023). "Type 1 diabetes (T1D) is a lifelong disease with a multifactorial treatment, which requires exogenous insulin therapy, calculated insulin doses for every meal and constant attention to blood glucose levels." (PMID 38004219, 2023). "Insulin omission to reduce the body weight is a unique, type 1 diabetes-specific eating purging behavior." (PMID 37665472, 2023). "Managing type 1 diabetes relies on daily, lifelong insulin administration and careful monitoring of dietary regimens and BGCs." (PMID 37458220, 2023). "Since its introduction in the 1970s, insulin pump therapy has generated a particular interest, representing an important advance in the management of patients with type 1 diabetes." (PMID 37185052, 2023). "In the treatment of type 1 diabetes, the importance of the relationship between the intensity of insulin treatment, glycaemic control, and the reduction of complications was clarified by the DCCT study." (PMID 37685946, 2023). "Our results provide evidence for a novel adjunct to insulin and metformin as potential initial treatment for adult-onset type 1 diabetes." (PMID 37076476, 2023). "This study provides the first clear evidence that an adjunctive combination of saxagliptin and vitamin D to insulin and metformin can be valuable in the management of adult-onset type 1 diabetes." (PMID 37076476, 2023). "For example, prior to the introduction of biotechnology-produced insulin, pig-derived insulin was the primary treatment for type I diabetes, and digestive enzymes harvested from porcine pancreases are used to treat human pancreatic insufficiency." (PMID 36984860, 2023). "Defective insulin secretion leads to type I diabetes mellitus (T1DM) and affects adolescents and children." (PMID 36811724, 2023). "Type 1 diabetes (T1D) is a T-cell mediated autoimmune disease in which the insulin-producing beta cells are destroyed." (PMID 36619657, 2023). "At least 50% of diabetic dogs resemble the clinical feature of inadequate insulin production in Type I diabetes in humans." (PMID 37570288, 2023). "Established type 1 diabetes, requiring lifelong insulin therapy and management to control blood sugar levels." (PMID 38094298, 2023). "The first hybrid closed-loop (HCL) system, with automated insulin delivery but still requiring user inputs, was approved for the treatment of Type 1 Diabetes (T1D) by the U.S. Food and Drug Administration in September 2016." (PMID 37511644, 2023). "One example of a recommendation that was changed after the PC is the case of the rapid-acting insulin analogues for type 1 diabetes, which resulted in a recommendation favourable to the adoption of the medicines into the SUS." (PMID 37438823, 2023). "The oral bioavailability of the insulin-loaded DLPC MSNs was able to decrease 55% of the original blood glucose level in STZ-induced type 1 diabetic rats, which was significantly greater than that of free oral insulin and that of unmodified MSNs." (PMID 37765234, 2023). "The main characteristic of type I diabetes is the destruction of insulin-producing pancreatic β-cells so that these patients cannot make insulin." (PMID 37342663, 2023). "This procedure has been successfully performed on patients with type I Diabetes, providing exogenous insulin independence for several years." (PMID 36911193, 2023). "Type 1 diabetes mellitus (T1D) is a chronic autoimmune disease in which insulin-producing β cells in the pancreas are destroyed by their autoimmune reaction driven by autoimmune T-cells." (PMID 37515018, 2023). "Type 1 diabetes (T1D) is characterized as the inability to produce and secrete insulin predominantly due to autoimmune T-cell-mediated destruction of islet β-cells." (PMID 37239940, 2023).
type 1 diabetes (continued). "In type 1 diabetes, the most common form of treatment to control glycemia is the use of insulin in the form of injections or special insulin pumps." (PMID 37373398, 2023). "Type 1 diabetes is an organ-specific autoimmune disease resulting from the chronic autoimmune-mediated destruction of insulin-producing pancreatic beta cells." (PMID 36207582, 2023). "We concede that the proportion of type 1 diabetes patients receiving the current standard of care (‘intensive insulin therapy’ in DCCT nomenclature) and nonetheless developing diabetic complications is thankfully relatively small." (PMID 36701305, 2023). "Previously, the symptomatic and endocrine responses to hypoglycaemia have been studied for insulin detemir, insulin degludec and glargine U100 in healthy individuals and in individuals with type 1 diabetes." (PMID 37308751, 2023). "Maternal diet, lipid metabolism, insulin dosing and glycaemia are important modifiable factors in the pathophysiology of perinatal complications in type 1 diabetes pregnancy." (PMID 37615689, 2023). "In a randomised controlled trial comprising 34 patients with type I diabetes, supplementation with CoQ10 (100 mg/day for 3 months) had no significant benefit on glycaemic control (blood glucose level, HbA1c, insulin dose)." (PMID 36830072, 2023). "The enhanced LDL-c levels in individuals with type 1 diabetes with poor glycaemic control are partly explained by the catabolic effects of insulin on LDL-c." (PMID 38032368, 2023). "The InRange trial also explored differences in treatment with insulin degludec U100 and insulin glargine U300 in people with type 1 diabetes using CGM data." (PMID 38089060, 2023). "Type 1 diabetes (T1D) is an organ-specific autoimmune disease with selective destruction of β-cells in islets and dysfunction of insulin secretion, affecting more than 490 thousand of the world's children." (PMID 36960388, 2023). "Type 1 diabetes is a chronic autoimmune disorder characterized by the inability to produce insulin and resulting in dysregulated blood glucose levels." (PMID 37960229, 2023). "Differentiating patient-derived iPSCs to functional cell types such as insulin-producing beta-cells for restoring the function of the pancreatic endocrine cells in Type I diabetes patients is an attractive long-term aim in the regenerative medicine field." (PMID 36697417, 2023). "Type 1 diabetes is an autoimmune disease in which islet specific T cells are thought to play a pivotal role in destroying insulin producing β cells." (PMID 37283770, 2023). "The insulin monomer is prone to aggregation with the formation of amyloid aggregates; amyloid-like fibrils can form even at the injection site of insulin in patients with insulin-dependent diabetes." (PMID 37833898, 2023). "TNF-α blocking agents have demonstrated efficacy in preserving insulin secretion in new onset type 1 diabetes; initially in a pilot study of etanercept and more recently, in a phase 1/2 clinical trial of golimumab." (PMID 38096190, 2023). "CGM should be provided to all pregnant women with type 1 diabetes who use intensive insulin therapy." (PMID 37680884, 2023). "Individuals with type 1 diabetes and their caregivers should be guided regarding appropriate fruit consumption and insulin administration." (PMID 37960229, 2023). "Type 1 diabetes mellitus (T1D)—one of the most widespread diseases of our time—is a chronic disease that results from the autoimmune destruction of insulin-producing β-cells in the islets of Langerhans in the pancreas." (PMID 36983153, 2023). "Type 1 diabetes results from organ-specific autoimmunity, which eliminates most of the insulin-producing pancreatic beta cells." (PMID 37488322, 2023). "The majority of guidelines suggest using CC to calculate mealtime insulin dosage for type-1 diabetes." (PMID 37845717, 2023). "Type 1 diabetes (T1D) is an autoimmune disease characterized by the destruction of pancreatic β-cells, resulting in insufficient insulin secretion." (PMID 36677050, 2023).